B2M (beta-2-microglobulin)
Diseases named in the same sentence as B2M in open-access papers (continued):
Sharing a sentence is not in itself a finding about the gene and the disease.
tumor (continued). "To simulate the immune evasion mechanism of HLA-I downregulation in tumor cells in vitro, we first knocked out TAP1 and TAP2 simultaneously and knocked out B2M genes in several solid tumor cells (A375, A549 and 786-O) using CRISPR/Cas9 technology, respectively." (PMID 36612246, 2022). "Mutant B2M status significantly increased the odds of peritoneal metastasis, whereas the primary tumor site was not related to the metastatic pattern." (PMID 34168989, 2021). "Unlike wildtype tumors, B2m-deficient MC38 tumors showed indistinguishable growth kinetics in these two groups of mice, demonstrating that tumor cell recognition by CD8+ T cells is essential for the antitumor effect caused by T cell-specific LSD1 depletion." (PMID 34819502, 2021). "In fact, while NK cells from B2m−/− do not reject B2m−/− T cell blasts, they can respond to Yac-1 tumor cells." (PMID 33467442, 2021). "Conditioned media of STC1+PENK− cancer-associated stromal cells (isolated from a Gleason 3 tumor) were still able to induce NCCIT to down-regulate scTF and up-regulate B2M but without induction of PENK." (PMID 34911496, 2021). "In our laboratory, we have also demonstrated that the genetic depletion of B2M impedes the immune surveillance on MMRd tumors; however, the absence of B2M does not preclude tumor regression upon CPIs." (PMID 34072037, 2021). "The B2M is the subunit necessary for antigen presentation by MHC-1 and the tumor resistant anti-CTLA-4 or anti-PD-1 therapy no longer express B2M." (PMID 33644048, 2021). "In general, B2M protein expression was significantly reduced in the tumor but not in the stroma of DB-CRCs in the discovery and validation cohorts as well as in both cohorts combined." (PMID 34197832, 2021). "Interestingly, these immunosuppressive protein markers were also significantly (* p < 0.05) correlated with an increased expression of certain tumor markers, such as CD44, B2M, HER2/ErbB2, S6, B7-H3, ER alpha and S100B." (PMID 34944780, 2021). "Ablation of antigen presenting machinery by knocking out B2M did not affect immune-mediated tumor killing, indicating the absence of an allogeneic response." (PMID 33446805, 2021). "The investigators detected B2M mutations in 32% (39/121 cases) of dMMR/MSI tumors and none of these patients had tumor recurrence while 18% of B2M wild-type tumors developed disease recurrence." (PMID 33467526, 2021). "The in vitro antitumor function of these multiplex double‐knockout (DKO) (TRAC and B2M) and triple‐knockout (TKO) (TRAC, B2M, and PD‐1) CAR‐T cells revealed higher cytokine production and potent cytotoxic activity against tumor cells compared to standard CAR‐T cells." (PMID 34188916, 2021). "B2M positively correlated with multiple infiltrating immune cell types, such as NK cells, CD4+ T effector memory cells (TEM), and CD8+ TEM, which play a critical role in anti-tumor response." (PMID 33658560, 2021). "Although our finding does not translate into enhanced killing capacity of tumor cells in vitro and in vivo, we observed a slightly increased capacity of NKG2DΔNK mice to reject B2m−/− splenocytes." (PMID 32052406, 2020). "Attenuated B2M expression may also hold important consequences for therapies with immune checkpoint inhibitors (ICI), since proper tumor antigen presentation is required for the effective action of ICI." (PMID 33260693, 2020). "The tumor cells in cluster B showed similar characteristics to those of tipifarnib-resistant tumor cells, including downregulation of the RAS and MAPK signaling pathways and upregulation of IGFBP7, MDK, and B2M mRNA." (PMID 32460812, 2020). "Hierarchical clustering of cMS candidates on all tumor samples revealed the existence of three distinct populations of cMS, which was retained in B2M-wild-type (n = 99) but not in B2M-mutant (n = 33) tumors." (PMID 32958755, 2020).
tumor (continued). "The B2M protein is an irreplaceable HLA1 molecule, and a lack of B2M negatively affects tumor antigen presentation and contributes to resistance to anti-PD-1 therapy." (PMID 32000802, 2020). "Although several primary tumour regions in Tumours 2 and 3 showed biallelic B2M inactivation this was not propagated to any of the four lymph node metastases." (PMID 31949146, 2020). "Importantly, B2M (Beta-2-Microglobulin), essential for expression of MHC class I and thus immunologic targeting of tumor cells by CD8+T cells, was downregulated (log2 T/N < 0) in both LST and HST." (PMID 31409279, 2019). "Sanger sequencing was performed for the three coding exons of B2M on 121 dMMR and a subsample of 108 pMMR tumours; 52 with recurrence and 56 without." (PMID 31062389, 2019). "The B2M‐mutant tumours were, however, less locally invasive with none exhibiting extramural invasion, significantly fewer than among the B2M‐wild‐type tumours: 0% (none of 38) versus 16% (12 of 74), P = 0.009." (PMID 31062389, 2019). "The common expression of B2M and MHC-I on tumor cells of EMPD reported herein demonstrates that EMPD retains the cellular antigen presenting machinery that is widely regarded as beneficial for immune targeting suggesting that EMPD patients have a greater likelihood of responding to immunotherapy." (PMID 31692889, 2019). "With median follow‐up of 7.4 years, none of the 39 B2M‐mutant tumours recurred, compared with 14 of 77 (18%) B2M‐wild‐type tumours (P = 0.005); six at local and eight at distant sites." (PMID 31062389, 2019). "Additionally, since response to checkpoint blockade has been associated with expression of major histocompatibility complex class I (MHC-I) and beta-2-microglobulin (B2M), we evaluated EMPD tumor cell expression of MHC-I and B2M in our cohort." (PMID 31692889, 2019). "Altogether, the precise TALEN®-mediated inactivation of B2M coupled with insertion of an NK- cell inhibitor enabled the generation of allogeneic CAR T-cells, resistant to host T- and NK-cells, with improved persistence and long-term anti-tumor activity." (PMID 30400835, 2018). "The fact that B2M is primarily expressed by the stroma of the ESCC tissue strengthens our hypothesis that in ESCC, MSCs-derived B2M promotes tumor-initiation and invasion via enhancing EMT, resulting in an adverse prognosis for the patients." (PMID 29615660, 2018). "Validation of B2M expression in a responder (Pat272) showed no changes in tumor-specific expression over time." (PMID 29070816, 2017). "Mice that lacked NK cells showed a significant increase in B2M-deleted relative to B2M+/+ tumor cells." (PMID 29070816, 2017). "We characterized the expression of the immunologic markers MHC Class I and B2M and the T cell inhibitory ligands PD-L1 and cytotoxic T lymphocyte antigen-4 (CTLA-4) by gene analysis on tumor and cell line microarrays and determined cell line protein expression of these markers by flow cytometry." (PMID 29137242, 2017). "We quantified the COX-2 mRNA levels per mg tissue, as well as relative to the levels of two different housekeeping genes GAPDH and B2M, in 60 paired samples of normal colorectal mucosa and corresponding non-necrotic tumor tissue." (PMID 24383454, 2014). "Importantly, mutations potentially contributing to immune evasion have been described in HLA-A in a small percentage of LUSC and of B2M and CD58 in other tumor types." (PMID 24162015, 2013). "One explanation for the variation may be that the real-time values are normalized to B2M and GAPDH, whose expression may vary between tumor samples." (PMID 22272937, 2012). "HPRT1, B2M, and RPL29 in tumor stomach tissues passed the normality in DAP- and SW-tests." (PMID 20507635, 2010). "IFNγ pathway mutations were found at similar frequencies compared to antigen presentation mutations such as in B2M, TAP, or HLA molecules, suggesting that the pressure induced by T cells is not potent enough in most tumours to select for these types of mutations." (PMID 39746898, 2025).
tumor (continued). "Therefore, we investigated the evolutionary history of cancer associated gene sequences across 384 mammalian taxa, to detect signatures of selection across categories of oncogenes (GRB2, FGL2 and CDC42), tumour suppressors (LITAF, Casp8 and BRCA2) and immune genes (IL2, CD274 and B2M)." (PMID 38773187, 2024). "However, lack of B2m in MC38 tumor cells resulted in a significant decrease in tumor-infiltrating macrophages, DCs and CD8+ T cells, without appreciable impact in CD4+, Tregs, or NK lymphocytes." (PMID 38427670, 2024). "In our studies, only B2M and not HLA-A expression in tumor biopsies taken during ongoing immunotherapy correlated with clinical benefit, while tumor HLA-A or B2M measured before start of therapy (baseline samples) did not correlate to subsequent clinical outcome." (PMID 38455061, 2024). "The results presented here may help to define a more precise immunological signature of patients affected by CRC, highlighting the role of the tumor microenvironment and extending our knowledge of different immunological signatures involving alterations in complexes driven by CIITA and B2M." (PMID 37046620, 2023). "Importantly, CD8+ T cells and tumor-specific MHC-I played a crucial role in the tumor control mediated by Pikfyve-depletion, as depletion of CD8+ T cells by anti-CD8 antibody or disruption of MHC-I by B2m-knockout rescued progression of the tumors derived from Pikfyve-null cancer cells." (PMID 38011559, 2023). "Overall, these results suggest that, unlike other tumor types, MSI CRCs with B2M and JAK1/2 mutations are responsive to PD-1 inhibitors, indicating that the mechanism of resistance to anti-PD-1 therapy in CRC may be different from that in other solid tumors." (PMID 37686520, 2023). "However, in the context of tumor cells, the overexpression of "Don't eat me" signals like CD47, PD-L1, and beta-2 microglobulin (B2M), an anti-phagocytic subunit of the primary histocompatibility complex class I, enables these cells to evade macrophages and proliferate uncontrollably." (PMID 37822610, 2023). "To block direct presentation, we used CRISPR to delete B2M from the cancer cells to generate cancer cells that were unable to express MHCI even following IFNg stimulation, and these cells were unable to directly present antigen to tumor-specific CD8 T cells in vitro (Fig. 2cii)." (PMID 37072485, 2023). "Tumor cells demonstrated enriched expression of the proteasome and immunoproteasome subunits Psmb8 and Psmb9 and major histocompatibility complex class I (MHC I) genes H2-K1, H2-D1, and B2m, consistent with upregulation of antigen processing and presentation machinery." (PMID 37041154, 2023). "Compared with the Vδ1 and Vδ3 T cell and KIR gene sets, the other marker gene sets showed no or only weak association between expression level and B2M status, indicating that our findings were not solely driven by a generally more inflamed state of B2MMUT tumours." (PMID 36631610, 2023). "The expression levels of B2M(p = 2.926e-05), HLA-C(p = 2.628e-03), HLA-E(p = 5.5166e-08), HLA-F(p = 9.376e-03), TAP1(p = 1.972e-09), TAP2(p = 1.245e-04) and TAPBP (p = 2.652e-12)in tumor tissues of dMMR patients were significantly higher than those of pMMR patients." (PMID 36527024, 2022). "B2M is a part of the constant region of major histocompatibility class I (MHC I) that is constitutively expressed on all nucleated cells, while PD-L1 is conditionally expressed in monocytes and MDMs and has been reported to regulate other immune cells in the tumor microenvironment." (PMID 36077152, 2022). "Also, TGFB1, ENG, B2M, HLA-F, SELPLG, and ITGB2 were significantly increased in tumor-associated macrophages, compared with those nontumor-associated macrophages." (PMID 36249427, 2022). "Importantly, B2m ablation led to the acceleration of tumor growth and the eradication of CD8+ T cells, irrespective of WHSC1 overexpression." (PMID 35230972, 2022).
tumor (continued). "The lack of HLA-C and B2M limits the activation of tumor-infiltrating T cells." (PMID 35173763, 2021). "Interestingly, three tumors with LOH-6 had no LOH-15 and the only LOH-6-free tumor V315 showed CN-LOH-15 involving entire chromosome 15 including the B2M gene." (PMID 34680201, 2021). "In our study, only one patient with a B2M-mutant tumor and several metastases not restricted to peritoneal or lymphatic sites was treated with a combination of anti-CTLA-4 and anti-PD-l antibodies (ipilimumab and nivolumab) and demonstrated SD as best response." (PMID 34168989, 2021). "Furthermore, restoring the expression of MARC2 could increase the expression of HLA-C and B2M via PPARA-related lipid metabolism signaling pathways, which could facilitate tumor antigen presentation to the tumor-infiltrating T cells." (PMID 35173763, 2021). "Thus, both of B2M and CIITA contributed to the incapability of forming tumor-like mass." (PMID 32746912, 2020). "Similarity between the in situ and invasive tumor component of each case by marker, measured using cosine similarity, showed the highest similarity between the two components for CK7, followed by MHC-I, B7-H4, B2M, CK20, and B7-H3 in order of least to greatest change." (PMID 31692889, 2019). "B2M status was not significantly related to any tumour characteristics other than MMR status." (PMID 31062389, 2019). "Considering that B2M is primarily expressed by the stroma of the ESCC tissue, our results further strengthen our hypothesis that in ESCC, MSCs-derived B2M promotes tumor-initiation and invasion via enhancing EMT, resulting in an adverse prognosis for the patients." (PMID 29615660, 2018). "By targeting both the MHC class I complex (beta-2-microglobulin) and a broadly expressed sodium-potassium ATPase-subunit (CD298) with platinum-conjugated antibodies, human immune cells, stem cells as well as tumor cells could be multiplexed in the same single-cell assay." (PMID 30018331, 2018). "Expression of human beta-2-microglobulin (B2M), a human housekeeping gene, was detected in bone homogenates from MCF7-inoculated mice in 5/10 (50%) −E2 mice and 5/8 (63%) +E2 mice by qPCR, making this the second most sensitive method of MCF7 tumor cell detection in bone after flow cytometry." (PMID 30250146, 2018). "Thus, knocking out the β2-microglobulin in the tumor cells would eliminate TSPY-peptide MHC-I complex formation and presentation on the cell surface, thereby abolishing such CD8+ cytotoxic T cell attacks on these B2m negative but TSPY-positive tumor cells, which were then grew to larger tumor foci." (PMID 40563082, 2025). "Notably, B2m expression exhibited significant attenuation in response to IFNγ for DKO cells, suggesting that MBNL proteins contribute to the modulation of the tumor-immune interaction in part via alterations in expression levels of components of MHC Class I antigen presentation." (PMID 40305509, 2025). "However, B2M expression was increased in CD8 high, PD-L1+ tumors which suggest that functional anergy induced through PD-1 on T-cells interacting with tumor PD-L1 may be a more dominant pathway of immune escape and B2M downregulation may be of lesser consequence in its presence." (PMID 38455061, 2024). "Unlike other tumor types in which B2M mutations have been associated with a lack of response to immune checkpoint inhibitors, among immunotherapy-naïve CRC patients, up to 85% of tumors with B2M mutations achieve clinical benefit with immunotherapy, most notably in MSI-H tumors." (PMID 37686520, 2023). "Interestingly, the pre-vaccinated tumor expressed B2M, while the post-vaccinated tumor did not, which could explain the initial response to immune-related therapy and the progression during ICI treatment." (PMID 36615128, 2022).
tumor (continued). "Based on the analysis of the genetic alteration profile of the tumor, there were no preexisting genomic alterations in antigen processing and presentation as well as immune response, such as B2M, PTEN, STK11, which might account for de novo resistance to ICI treatment." (PMID 34898561, 2021). "As 95% (110 of 116) of the tumours tested were stage II, consistent with the 91% overall proportion of stage II CRCs in QUASAR, we could not meaningfully compare propensity for nodal spread in B2M‐mutant and wild‐type tumours: 2.6% (one of 39) versus 3.9% (three of 77) were node‐positive." (PMID 31062389, 2019). "No mutations were observed in the gene encoding beta-2-microglobulin (B2M), the required subunit necessary for surface expression of the MHC class I molecule, or the gene encoding interferon-receptor-associated Janus kinase 2 (JAK2) in either of the tumor specimens." (PMID 31703593, 2019). "Image quantification revealed that TUNEL+ cell density was significantly higher in CRATERs compared with elsewhere in the tumor following CpG ODN treatment of WT, but not B2M KO, tumors." (PMID 41109214, 2025). "Depletion of Ptdss1 in tumor cells increased expression of interferon-γ (IFN-γ)–regulated genes, including B2m, Cxcl9, Cxcl10, and Stat1, even in the absence of IFN-γ stimulation in vitro." (PMID 40929270, 2025). "Compared to wt tumors, the absence of B2m, Jak1 and LMP2 expression on tumor cells resulted in a significant reduction of monocytic myeloid-derived suppressor cells (M-MDSC) in the TME." (PMID 38427670, 2024). "The absence of B2m, Jak1 and LMP2 expression on EMT6 tumor cells did not impact the infiltration of macrophages, effector CD4+ or CD8+ T cells, or CD4+ regulatory T cells (Tregs)." (PMID 38427670, 2024). "Using previously validated immune gene signatures from bulk RNA datasets to estimate immune cell abundances, we found that B2M and CD1D but not CD1B were significantly enriched on both tumor and DCs cells from patients responding to ICT." (PMID 37077920, 2023). "Knocking down the B2M gene in the M202 and M233 human melanoma cell lines resulted in the absence of MHC-I molecules expressed on their surface, and the absence of tumor-specific T-cell recognition and cytotoxicity." (PMID 33859752, 2021). "Garrido and colleagues have proposed that tumor MHC-I downregulation or loss is categorized as “soft” and “hard” alterations, depending on whether the loss of MHC-I expression is reversible (such as transcriptional downregulation) or not (for instance, loss of both copies of a gene such as B2M)." (PMID 34201655, 2021). "In contrast, class I HLA-lacking B2M knockout (B2M−/−DRB1−/−) ECs and HLA-devoid K562 tumor cells were significantly vulnerable to NK cell cytotoxicity." (PMID 33423156, 2021). "In conjunction with these data, IHC analysis of the patient tumor revealed that Ki-67-negative, non-cycling cells showed a higher immunoreactivity against IGFBP7, MDK, and B2M." (PMID 32460812, 2020). "Markers of tumor burden like M-protein involved serum FLC, involved-to-uninvolved FLC ratio, beta-2 microglobulin, and BM plasmacytosis were all lower in the without CRAB/FLC cohort." (PMID 32376870, 2020). "Presence of somatic variants in genes related to antigen presentation, including HLA-A, HLA-B, HLA-C, B2M (β-2-microglobulin), TAP2, and PSMB8 (LMP-7), did not predict tumor classification." (PMID 30824826, 2019). "Indeed, co-transfer of WT host-type spleen DCs (which contain CD8α+ DCs) and T cells into allogeneic B2m−/− recipients, which are functionally deficient in antigen presentation, induced a significant CD8+ T cell-mediated GVL response, leading to prolonged survival of recipients without tumor." (PMID 30774630, 2019). "Significant expression increase from normal to tumor stomach tissues (p < 0.05) were observed in HPRT1 (p = 0.011) and 18S rRNA (p = 0.021), but not in ACTB (p = 0.058), GAPDH (p = 0.918), B2M (p = 0.740), or RPL29 (p = 0.208)." (PMID 20507635, 2010).